RNU6-714P (RNA, U6 small nuclear 714, pseudogene)
Gene: Small nuclear RNA gene on chromosome 9 (92,820,977 to 92,821,079, forward strand). Ensembl gene ENSG00000252772.
Homologues: Orthologues: chimpanzee U6 (98% identical), dog U6 (67% identical), rat LOC120101210 (58% identical), mouse Gm22279 (57% identical), mouse Gm54642 (57% identical). Paralogues in human: RNU6-798P (92% identical), RNU6-316P (88% identical), RNU6-55P (88% identical), RNU6-821P (87% identical), RNU6-954P (87% identical), U6 (86% identical), RNU6-1193P (85% identical), RNU6-1269P (85% identical), RNU6-368P (85% identical), RNU6-538P (85% identical), RNU6-1320P (84% identical), RNU6-599P (84% identical), and 1285 more.